PRAMEF11 (PRAME family member 11)
Tractability: No criterion of Open Targets' tractability assessment is met for any kind of drug.
Gene: Protein-coding gene on chromosome 1 (12,824,605 to 12,831,410, reverse strand). Ensembl gene ENSG00000239810.
Gene Ontology:
Molecular function: ubiquitin-like ligase-substrate adaptor activity
Biological process: proteasome-mediated ubiquitin-dependent protein catabolic process; negative regulation of apoptotic process; negative regulation of cell differentiation; negative regulation of DNA-templated transcription; positive regulation of cell population proliferation
Cellular component: Cul2-RING ubiquitin ligase complex; cytoplasm
Genetic constraint (gnomAD): Loss-of-function variants: 16 observed, 26.65 expected, observed/expected ratio (o/e) 0.6, 90% interval 0.41 to 0.91. The upper end of that interval is the gene's LOEUF score, 0.91, which puts it in group 3 of 6, group 1 being the genes least tolerant of losing a copy. Missense variants: 549 observed, 466.16 expected, observed/expected ratio (o/e) 1.18, 90% interval 1.1 to 1.26. Synonymous variants: 192 observed, 185.62 expected, observed/expected ratio (o/e) 1.03, 90% interval 0.92 to 1.17.
Homologues: Orthologues: mouse Pramel13 (46% identical), rat Pramef12 (44% identical), rat Pramef8 (43% identical), mouse Pramel12 (43% identical), rat LOC120103107 (42% identical), mouse Pramel15 (42% identical), mouse Pramel16 (42% identical), mouse Pramel31 (42% identical), mouse Gm13040 (41% identical), mouse Gm13043 (41% identical), mouse Gm13057 (41% identical), rat Pramef5 (41% identical), and 78 more. Paralogues in human: PRAMEF15 (97% identical), PRAMEF25 (96% identical), PRAMEF26 (96% identical), PRAMEF4 (96% identical), PRAMEF5 (95% identical), PRAMEF6 (95% identical), PRAMEF9 (95% identical), PRAMEF27 (95% identical), PRAMEF20 (81% identical), PRAMEF12 (62% identical), PRAMEF8 (61% identical), PRAMEF7 (61% identical), and 12 more.